PLEKHG3 (pleckstrin homology and RhoGEF domain containing G3)
Description:
Plays a role in controlling cell polarity and cell motility by selectively binding newly polymerized actin and activating RAC1 and CDC42 to enhance local actin polymerization.
Synonyms: KIAA0599; ARHGEF43
Tractability: PROTAC: ubiquitination databases record sites on it; its protein half-life has been measured.
Gene: Protein-coding gene on chromosome 14 (64,704,102 to 64,750,249, forward strand). Ensembl gene ENSG00000126822.
Subcellular location: Cytoplasm, cytoskeleton
Subcellular location (Human Protein Atlas): Plasma membrane; Cytosol
Pathways (Reactome):
Signal Transduction: CDC42 GTPase cycle; RAC1 GTPase cycle; RHOA GTPase cycle; RHOG GTPase cycle; RHOQ GTPase cycle
Gene Ontology:
Molecular function: actin binding; guanyl-nucleotide exchange factor activity; small GTPase binding
Biological process: regulation of cell migration; regulation of establishment of cell polarity; regulation of small GTPase mediated signal transduction
Cellular component: cytosol; cytoskeleton
Genetic constraint (gnomAD): Loss-of-function variants: 54 observed, 83.68 expected, observed/expected ratio (o/e) 0.65, 90% interval 0.52 to 0.81. The upper end of that interval is the gene's LOEUF score, 0.81, which puts it in group 3 of 6, group 1 being the genes least tolerant of losing a copy. Missense variants: 1,390 observed, 1,565.5 expected, observed/expected ratio (o/e) 0.89, 90% interval 0.85 to 0.93. Synonymous variants: 587 observed, 631.52 expected, observed/expected ratio (o/e) 0.93, 90% interval 0.87 to 1.
Homologues: Orthologues: chimpanzee PLEKHG3 (99% identical), macaque PLEKHG3 (96% identical), dog PLEKHG3 (84% identical), pig PLEKHG3 (82% identical), mouse Plekhg3 (81% identical), rat Plekhg3 (80% identical), guinea pig PLEKHG3 (79% identical), rabbit PLEKHG3 (72% identical), tropical clawed frog plekhg3 (44% identical), zebrafish si:ch73-212j7.3 (20% identical), zebrafish si:ch73-212j7.3 (13% identical).
Diseases named in the same sentence as PLEKHG3 in open-access papers:
PLEKHG3 is named in the same sentence as 1 disease in open-access papers, as found by Europe PMC text mining. Sharing a sentence is not in itself a finding about the gene and the disease. The quoted sentences say what the papers report.
autism (2 papers, 2014 to 2022). Persistent deficits in social interaction and communication and interaction as well as a markedly restricted repertoire of activity and interest as well as repetitive patterns of behavior. "Since VK2 is located in the regulatory region of PLEKHG3 gene in the 14th chromosome, a likely candidate contributing to the risk of autism, the fold is potentially of huge biological relevance." (PMID 25500730, 2014). "The VK1 sequence of the PLEKHG3 gene is expressed in the brain and is linked to the development of autism." (PMID 25500730, 2014). "Noteworthy, the PLEKHG3 gene is a potential candidate contributing to the risk of autism." (PMID 25500730, 2014). "This sequence is a variation in the d(GGGAGCG) repeat, found in the regulatory region of the PLEKHG3 human gene related to autism." (PMID 36014524, 2022).